BORCS8-MEF2B (BORCS8-MEF2B readthrough)
Synonyms: formerly MEF2BNB-MEF2B
Gene: Protein-coding gene on chromosome 19 (19,145,569 to 19,192,158, reverse strand). Ensembl gene ENSG00000064489.
Genetic constraint (gnomAD): Loss-of-function variants: 15 observed, 29.75 expected, observed/expected ratio (o/e) 0.5, 90% interval 0.34 to 0.78. The upper end of that interval is the gene's LOEUF score, 0.78, which puts it in group 3 of 6, group 1 being the genes least tolerant of losing a copy. Missense variants: 453 observed, 480.53 expected, observed/expected ratio (o/e) 0.94, 90% interval 0.87 to 1.02. Synonymous variants: 202 observed, 203 expected, observed/expected ratio (o/e) 1, 90% interval 0.89 to 1.12.